ANKRD10 (ankyrin repeat domain 10)
Synonyms: FLJ20093
Tractability: PROTAC: ubiquitination databases record sites on it; its protein half-life has been measured.
Gene: Protein-coding gene on chromosome 13 (110,878,540 to 110,915,071, reverse strand). Ensembl gene ENSG00000088448.
Subcellular location (Human Protein Atlas): Nucleoplasm
Gene Ontology:
Molecular function: protein binding
Cellular component: nucleoplasm
Genetic constraint (gnomAD): Loss-of-function variants: 16 observed, 23.47 expected, observed/expected ratio (o/e) 0.68, 90% interval 0.46 to 1.03. The upper end of that interval is the gene's LOEUF score, 1.03, which puts it in group 4 of 6, group 1 being the genes least tolerant of losing a copy. Missense variants: 493 observed, 527.38 expected, observed/expected ratio (o/e) 0.93, 90% interval 0.87 to 1.01. Synonymous variants: 250 observed, 224.19 expected, observed/expected ratio (o/e) 1.12, 90% interval 1 to 1.24.
Homologues: Orthologues: chimpanzee ANKRD10 (99% identical), macaque ANKRD10 (92% identical), pig ANKRD10 (85% identical), rat Ankrd10 (81% identical), mouse Ankrd10 (78% identical), guinea pig ANKRD10 (77% identical), dog ANKRD10 (70% identical), tropical clawed frog ankrd10 (54% identical), zebrafish ankrd10a (43% identical), zebrafish ankrd10b (40% identical). Paralogues in human: ANKRD6 (20% identical), NRARP (7% identical).
Diseases named in the same sentence as ANKRD10 in open-access papers:
ANKRD10 is named in the same sentence as 5 diseases in open-access papers, as found by Europe PMC text mining. Sharing a sentence is not in itself a finding about the gene and the disease. The quoted sentences say what the papers report.
glioblastoma (2 papers, 2022 to 2025). The most malignant astrocytic tumor (WHO grade IV). "ANKRD10 acted as a DNA methylation-driven gene in glioblastoma." (PMID 40909968, 2025). "Six methylation-driven gene biomarkers, including ANKRD10, could serve as a promising predictive model for glioblastoma patients." (PMID 36496360, 2022).
bladder cancer (1 paper, 2025). "A mechanistic study reveals that RBPMS suppresses bladder cancer cell migration by regulating alternative splicing of ANKRD10, which modulates MYC pathway activity through ANKRD10-2’s function as a transcriptional coactivator." (PMID 40044952, 2025).
melanoma (1 paper, 2025). A malignant, usually aggressive tumor composed of atypical, neoplastic melanocytes. "In our study, ANKRD10 exhibited high expression in melanoma patients." (PMID 40909968, 2025). "In GSE46517, IFFO1, ANKRD10, CLPB, TCAP, and POLG2 displayed high expression, but the expression levels of CHMP4A, ZDHHC11, and ANKMY1 were low in the melanoma group." (PMID 40909968, 2025).
cancer (2 papers, 2020 to 2025). A tumor composed of atypical neoplastic, often pleomorphic cells that invade other tissues. "Comprehensive analysis of transcriptome sequencing results pertaining to RBPMS and ANKRD10 revealed a potential interplay between RBPMS and ANKRD10-2 in influencing cancer progression, possibly through their influence on MYC target gene expression." (PMID 40044952, 2025). "RBPMS inhibits malignant tumor progression by binding to and cleaving ANKRD10 mRNA, which reduces translation to ANKRD10-2 and leads to a decrease in MYC transcriptional activity." (PMID 40044952, 2025). "However, studies on the role of ANKRD10 in cancer are limited." (PMID 40044952, 2025). "For ANKRD10, it is in a region dense with cancer-related genes (CDKN2ACDKN2B) and thus it is not surprising there may be multiple variants with independent regulatory effets." (PMID 32833970, 2020).
tumor (1 paper, 2025). "Based on our experimental findings, we suggest that therapeutic agents targeting the ANKRD10-2-MYC interaction pathway could offer a promising strategy for tumor suppression." (PMID 40044952, 2025). "Additionally, our investigation revealed that ANKRD10-2 knockdown mitigated the effect of RBPMS knockout on tumor cell migration." (PMID 40044952, 2025).